ALPI (alkaline phosphatase, intestinal)
Description:
Alkaline phosphatase that can hydrolyze various phosphate compounds.
Synonyms: IAP
Tractability: Small molecule: a high-quality ligand is known; it belongs to a druggable protein family. Antibody: its Gene Ontology location is reachable by antibodies, with high confidence; UniProt places it where antibodies can reach, with medium confidence; UniProt predicts a signal peptide or a membrane-spanning region; the Human Protein Atlas places it where antibodies can reach. PROTAC: ubiquitination databases record sites on it; a small molecule that binds it is known.
Target class: Enzyme; Phosphatase
Chemical probes: ML259
Gene: Protein-coding gene on chromosome 2 (232,456,125 to 232,460,753, forward strand). Ensembl gene ENSG00000163295.
Subcellular location: Cell membrane
Subcellular location (Human Protein Atlas): Plasma membrane
Pathways (Reactome):
Digestion and absorption: Digestion
Metabolism: Synthesis of PA
Metabolism of proteins: Post-translational modification: synthesis of GPI-anchored proteins
Gene Ontology:
Molecular function: protease binding; protein binding; alkaline phosphatase activity; magnesium ion binding; zinc ion binding; phosphatase activity
Biological process: dephosphorylation
Cellular component: extracellular region; plasma membrane
Genetic constraint (gnomAD): Loss-of-function variants: 50 observed, 54.42 expected, observed/expected ratio (o/e) 0.92, 90% interval 0.73 to 1.16. The upper end of that interval is the gene's LOEUF score, 1.16, which puts it in group 5 of 6, group 1 being the genes least tolerant of losing a copy. Missense variants: 692 observed, 731.21 expected, observed/expected ratio (o/e) 0.95, 90% interval 0.89 to 1.01. Synonymous variants: 322 observed, 306.04 expected, observed/expected ratio (o/e) 1.05, 90% interval 0.96 to 1.15.
Homologues: Orthologues: chimpanzee ALPI (99% identical), macaque ALPI (95% identical), dog ALPI (82% identical), mouse Akp3 (78% identical), mouse Alpi (78% identical), rat Alpi (77% identical), mouse Alppl2 (75% identical), rat Akp3 (75% identical), rat Alpg (75% identical), rat Alpp (75% identical), tropical clawed frog alpi (64% identical), zebrafish alpi.2 (58% identical), and 13 more. Paralogues in human: ALPG (87% identical), ALPP (87% identical), ALPL (54% identical).
Diseases named in the same sentence as ALPI in open-access papers:
ALPI is named in the same sentence as 41 diseases in open-access papers, as found by Europe PMC text mining. Sharing a sentence is not in itself a finding about the gene and the disease. The quoted sentences say what the papers report.
colitis (6 papers, 2018 to 2025). Inflammation of the colon. "Importantly, oral ALPI supplementation protected ALPI‐deficient mice from increased susceptibility to DSS‐induced colitis and from chronic colitis induced by recurrent non‐lethal infections by S. typhimurium." (PMID 29567797, 2018).
Obesity (3 papers, 2015 to 2024). Accumulation of substantial excess body fat. "In enteroids from patients with obesity, SCFAs (1 mM) increased (p < 0.05) ALPI mRNA expression 2.9-fold, but decreased (p < 0.01) MUC2 (0.4-fold) and CHGA (0.3-fold) mRNA expression." (PMID 38125020, 2023). "In addition, the SCFA-induced upregulation in the mRNA expression of ALPI correlated (r2 = 0.58, p < 0.05) with the upregulation of the tight junction protein zonula occludens-1 (ZO-1) in enteroids from patients with obesity." (PMID 38125020, 2023). "In enteroids from patients with obesity, treatment with the HDAC inhibitor SAHA induced an increase (p < 0.05) in ALPI (3.9-fold) mRNA expression and a decrease (p < 0.01) in MUC2 (0.2-fold) and CHGA (0.2-fold) mRNA expression." (PMID 38125020, 2023).
inflammatory bowel disease (2 papers, 2018 to 2024). A spectrum of small and large bowel inflammatory diseases of unknown etiology. "Herein, we report the first identification of biallelic‐inherited mutations in ALPI as a Mendelian cause of inflammatory bowel disease in two unrelated patients." (PMID 29567797, 2018). "ALPI mutations should be screened for in individuals with inflammatory bowel disease refractory to treatment." (PMID 29567797, 2018).
malnutrition (2 papers, 2016 to 2021). Inadequate nutrition resulting from poor diet, malabsorption, or abnormal nutrient distribution. "Thus, as in other animal models, a decline in ALPI activity is generally associated with malnutrition in fish, and perhaps to a less effective response for preventing bacterial invasion across the gut mucosal barrier." (PMID 34675821, 2021). "The lack of changes in ALPI activity and expression in the current trials could indicate that none of the diets induced a malnutrition state, as shown by the good growth performance values." (PMID 27898676, 2016).
adenoma (1 paper, 2024). A neoplasm arising from the epithelium. "The digestive brush-border enzyme ALPI is a marker of enterocytes and a GPI-AP downregulated in PIGA-mutant adenomas, indicating potential for enterocyte dedifferentiation to an immature crypt phenotype." (PMID 38546397, 2024).
Autoimmunity (1 paper, 2018). The occurrence of an immune reaction against the organism's own cells or tissues. "Herein, using whole‐exome sequencing (WES), we report the identification of ALPI mutations in two unrelated patients displaying severe intestinal inflammation and autoimmunity." (PMID 29567797, 2018). "Whether ALPI deficiency favoured autoimmunity‐related manifestations in P1 and P2 remains uncertain." (PMID 29567797, 2018).
C3 deficiency (1 paper, 2024). "In this study, we identified the ALPI gene as a constipation-associated novel gene because it was commonly detected in the Lop-induced constipation model and the C3 deficiency-induced constipation model of the present study." (PMID 39273477, 2024). "Based on the global gene profile, the ALPI gene was selected as one of the possible candidates as the unique gene associated with C3 deficiency-induced constipation." (PMID 39273477, 2024). "Taken together, our results suggest that ALPI can be considered a novel gene unique to constipation associated with C3 deficiency." (PMID 39273477, 2024). "In addition, these results suggest that alterations in the ALPI gene expression can act as one of the novel causes of C3 deficiency-induced constipation." (PMID 39273477, 2024). "Furthermore, to confirm our findings, we examined whether the recovery of ALPI expression can improve the constipation caused by C3 deficiency." (PMID 39273477, 2024). "Therefore, all the results from the study in epithelial cells suggest that the upregulation of ALPI expression may be tightly linked to the improvement of C3 deficiency-induced constipation." (PMID 39273477, 2024).
Constipation (1 paper, 2024). Infrequent or difficult evacuation of feces. "Thus, the expression of the ALPI gene and its effects on mucin secretion ability and water retention capacity in C3 deficiency-induced constipation was first investigated in the epithelial cells derived from the C3 KO mice." (PMID 39273477, 2024). "Specifically, the ALPI gene was selected as a novel gene candidate based on alterations during loperamide (Lop)-induced constipation and intestinal bowel disease (IBD)." (PMID 39273477, 2024).
germ cell neoplasms (1 paper, 2022). "Germ cell alkaline phosphatase is located in germ cell neoplasms, and levels of ALPI have been detected in over 75% of individual TGCT samples, primarily located in the cytoplasm or membrane." (PMID 35774118, 2022).
optic atrophy (1 paper, 2025). A disorder characterized by loss of optic nerve fibers. "In contrast, the lowest penetrance was seen for ALPI and optic atrophy (0.8%)." (PMID 41255976, 2025).
Salmonella Infections (1 paper, 2018). Infections with bacteria of the genus SALMONELLA. "This conclusion is in keeping with recent work showing how reduced expression of ALPI induced by recurrent non‐lethal Salmonella infections impairs intraluminal dephosphorylation/detoxification of LPS." (PMID 29567797, 2018).
infectious disease (1 paper, 2025). A disorder directly resulting from the presence and activity of a microbial, viral, or parasitic agent in humans. "In the weanling pig, the disrupted brush border lacks detoxifying enzymes such as intestinal alkaline phosphatase (ALPi) which further increases the risk of an infectious disease." (PMID 40159791, 2025).
inflammation (1 paper, 2018). Aberrant reaction of the microcirculation characterized by movement of fluid and leukocytes from the blood into extravascular tissues. "The necessity of an environmental trigger to uncover genetic susceptibility to intestinal inflammation in ALPI‐deficient individuals might account for the distinct ages of P1 and P2 at disease onset, leading to P1 developing very early onset IBDs while P2 presented as a teenager." (PMID 29567797, 2018).
ALPI also shares sentences with these, for which no sentence is quoted: tumor (4 papers); cancer (3); diabetes (3); colorectal cancer (2); Crohn disease (2); endotoxemia (2); Glucose intolerance (2); acute myocardial infarction (1); atopic dermatitis (1); atrial fibrillation and flutter (1); atrial septal defect (1); cardiac hypertrophy (1); cardiovascular disease (1); Chronic colitis (1); endometrial cancer (1); hypothyroidism (1); Infertility (1); intestinal diseases (1); intestinal inflammation (1); liver fibrosis (1); malignant mesothelioma (1); metabolic disorders (1); metabolic syndrome (1); myocarditis (1); non-melanoma skin carcinoma (1); prostate carcinoma (1); Sepsis (1); skin cancer (1).